INS (insulin)
Diseases named in the same sentence as INS in open-access papers (continued):
Sharing a sentence is not in itself a finding about the gene and the disease.
diabetic cardiomyopathy (continued). "Furthermore, the KEGG pathway analysis revealed that the differentially expressed genes were mainly enriched in signaling pathways such as insulin resistance, cellular apoptosis, and diabetic cardiomyopathy." (PMID 39619569, 2024). "This attenuation of diabetic cardiomyopathy was associated with decreased myocardial fatty acid oxidation rates (1.15 ± 0.19 vs 0.5 ± 0.1 μmol min−1 g dry wt−1 in the presence of insulin) but no change in glucose oxidation rates compared to the control group." (PMID 36978133, 2023). "In the early stages of diabetic cardiomyopathy, metabolic disturbances such as defective insulin signaling, excessive circulating insulin, impaired glucose uptake, elevations in myocardial fatty acid uptake, and mitochondrial dysfunction promote cardiac morphological and functional changes." (PMID 36742465, 2023). "Driven by reduced insulin signalling and/or insulin resistance in adipose tissue, liver, and skeletal muscle, pathological changes in these non-cardiac tissues contribute to the development and progression of diabetic cardiomyopathy." (PMID 35388880, 2023). "It is true that lowering blood glucose and increasing insulin sensitivity could improve the prognosis of diabetic cardiomyopathy." (PMID 35002528, 2022). "The genes in modules non-preserved in FTD disease, including lightgreen, midnightblue, and purple modules, were enriched in ‘prion disease’, and pathways related to metabolic disorders such as ‘diabetic cardiomyopathy’, ‘insulin signaling pathway’, and ‘aldosterone synthesis and secresion’." (PMID 36418457, 2022). "It is proposed that a combination therapy employing some metabolic agents or antioxidants with insulin may constitute an efficacious approach for the prevention of diabetic cardiomyopathy." (PMID 32244448, 2020). "However, in the setting of diabetic cardiomyopathy it has been shown that upregulation of the Insulin/PI3K/AKT pathway contributes to development of pathological hypertrophy and reduced systolic function." (PMID 33184414, 2020). "As cardiac insulin signaling may contribute to diabetic cardiomyopathy we analyzed the activity of the cardiac insulin signaling pathway." (PMID 33184414, 2020). "The pathogenesis of diabetic cardiomyopathy includes impaired myocardial insulin signaling, mitochondrial dysfunction, endoplasmic reticulum stress, impaired calcium homeostasis, abnormal coronary microcirculation, inappropriate neurohumoral activation, and maladaptive immune response." (PMID 31558158, 2019). "Nevertheless our results suggest that the use of high glucose and insulin free medium is sufficient to induce most of the characteristic phenotypes of diabetic cardiomyopathy, such as cardiac hypertrophy, increased NPPB expression and impaired contractile functions." (PMID 30291295, 2018). "To summarize, these findings suggest that our model of diabetic cardiomyopathy was constructed successfully and that exenatide could effectively ameliorate the impaired cardiac function compared with insulin treatment." (PMID 26759813, 2016). "Moreover, diabetic cardiomyopathy, clinically characterized by early diastolic dysfunction, followed by ventricular remodeling and, at later stages, systolic dysfunction was attenuated in insulin-treated STZ-diabetic rats." (PMID 38794147, 2024). "The increased reliance of the diabetic heart on fatty acids negatively impacts cardiac efficiency, impairs insulin metabolic signaling, elevates the production of ROS, increases mitochondrial membrane uncoupling, promotes lipotoxicity, and exacerbates diabetic cardiomyopathy." (PMID 38916917, 2024). "Thus, in view of the well-established role of MT function and energy stores in maintaining cardiac function and structure, it is evident that sarpogrelate, like insulin, may improve cardiac performance in diabetic cardiomyopathy." (PMID 39057635, 2024).
diabetic cardiomyopathy (continued). "Interestingly, functional enrichment analysis of KEGG terms indicated among the overrepresented pathways, Insulin, Thyroid, Diabetic complications, and Diabetic Cardiomyopathy pathways, as well as HIF-1, Ubiquitin proteolysis, and Mitogen-Activated Protein Kinase (MAPK) signaling." (PMID 37947656, 2023). "Therefore, the decline in the level of FST in diabetic cardiomyopathy might be explained by prolonged exposure to insulin." (PMID 34385917, 2021). "While the accumulation of TAGs, ceramides, diacylglycerols, and other lipid intermediates may promote myocardial insulin resistance, lipotoxicity, and cardiac myocyte apoptosis in diabetic cardiomyopathy, we encourage the reader to refer to the many excellent reviews already published on this topic." (PMID 33041869, 2020). "Since NF-κB signaling, defective insulin signaling, JNK signaling, and alterations in autophagy have been implicated in the pathogenesis of diabetic cardiomyopathy, we next determined if MuRF2−/− hearts had alterations in these processes that may explain their more severe phenotype." (PMID 26242235, 2015). "While these observations may seem paradoxical given calcineurin action, they seem to suggest a compensatory function of calcineurin, with regard to mitochondrial biogenesis and insulin sensitivity, which may be precluded in cardiac muscle of diabetic cardiomyopathy patients." (PMID 25216282, 2014). "Therefore, insulin signaling regulates both titin-isoform composition and titin phosphorylation in embryonic cardiomyocytes and could contribute to an altered diastolic function in diabetic cardiomyopathy." (PMID 35135591, 2022). "On the other hand, we have also found that ESA treatment can ameliorate these listed features of diabetic cardiomyopathy, but with no alteration in insulin or glucose plasma levels." (PMID 37893548, 2023). "We envisage that restoration of CTRP9 levels in diabetic cardiomyopathy might be a novel therapeutic strategy, but care must be taken that systemic insulin resistance is not aggravated by this approach." (PMID 36766785, 2023). "Similarly, the glucagon-like peptide-1 receptor agonist liraglutide, an antidiabetic agent that promotes insulin secretion, also stimulates myocardial PDH activity and glucose oxidation, thereby alleviating the diastolic dysfunction in a murine model of diabetic cardiomyopathy." (PMID 36211560, 2022). "In this mini-review, we have argued that LVH is a good surrogate marker of diabetic cardiomyopathy and discussed the trials targeting LVH as a manifestation of Stage B Cardiomyopathy, and potential mechanisms behind LVH regression in patients with T2DM or in insulin-resistant individuals." (PMID 34660744, 2021). "Incubating cardiomyocytes with insulin induces a dose-dependent increase in Hsp60 levels; this protein increases IGF-1 receptor expression and activity, and Hsp60 downregulation has been proposed to be a relevant mechanism for diabetic cardiomyopathy development." (PMID 31995605, 2020). "Others have suggested that myocardial overload and increased peripheral resistance resultant from exogenous insulin may be responsible for the observed diastolic dysfunction, rather than being symptoms of diabetic cardiomyopathy." (PMID 29773993, 2018). "In high fat diet (HFD)-induced diabetic cardiomyopathy, increased mTORC1 activity contributes to the development of diabetic cardiomyopathy, and mTORC1 inhibition prevents the development of HFD-induced diabetic cardiomyopathy by improving hepatic insulin sensitivity in obesity." (PMID 30572675, 2018). "While the changes seen in diabetic cardiomyopathy are vast, including alternations in metabolism, structural proteins, signal transduction, and ion channels, the crucial role of enhanced PPAR signaling has been central to the pathogenesis of this disease downstream of altered insulin resistance." (PMID 26242235, 2015).
schizophrenia (132 papers, 2006 to 2026). A major psychotic disorder characterized by abnormalities in the perception or expression of reality. "For example, a statistically significant association has been found between insulin levels and T allele carriers in Romanian paediatric patients with schizophrenia or bipolar disorder." (PMID 39966797, 2025). "Apart from being enriched in mTOR and EIF2 signaling in both sexes, the schizophrenia risk genes are also associated with an alteration of insulin signaling in females and with inflammatory signaling in males." (PMID 37188697, 2023). "Impairment of insulin action and metabolic dysregulation have traditionally been associated with schizophrenia, although the molecular basis of such association remains still elusive." (PMID 37085712, 2023). "Another MR study reported a genetic association between fasting insulin and schizophrenia, although the evidence attenuated after adjustment for BMI." (PMID 33711016, 2021). "The experience of childhood trauma in people with first-episode schizophrenia is associated with increased insulin (and the related c-peptide), providing a possible indication of insulin resistance." (PMID 34252192, 2021). "Some genetic studies of DM and schizophrenia have also revealed many overlapping risk genes, such as those involved in calcium, adipocytokine, insulin, and AKT signaling pathways." (PMID 34909279, 2021). "A recent genome-wide association study demonstrated that the two most significantly enriched pathways in patients with schizophrenia are associated with insulin secretion." (PMID 33255883, 2020). "In all pregnancies, with adjustment for the clustering of pregnancies within mothers, women with schizophrenia showed almost a 2-fold increased risk of both pathological oral glucose tolerance test and initiation of insulin treatment." (PMID 30762149, 2020). "In adjusted model, women with schizophrenia showed an almost 2-fold increased risk of pathologic oral glucose tolerance test, initiation of insulin treatment, and fast fetal growth." (PMID 30762149, 2020). "The EXOC4 gene which can cause schizophrenia in humans, is crucial for producing insulin and involved in protein and hormone metabolism." (PMID 31600309, 2019). "For example, genes associated with the illness of schizophrenia have independently been linked to regulation of fat mass, leptin signaling, insulin signaling, glucose metabolism, and inflammation." (PMID 30568606, 2018). "AKT1 is also especially relevant to intrinsic metabolic risk in schizophrenia since it is an important regulator of insulin signaling." (PMID 28804444, 2017). "Animal work suggests in turn that insulin can activate receptors in the brain inhibiting dopamine synthesis and release in areas implicated in schizophrenia psychopathology, such as the striatum." (PMID 29403343, 2017). "Chronic stress in schizophrenia may cause increased cortisol levels, disruption of the oxidant–antioxidant balance, and, in the future, insulin resistance and neuronal insulin resistance." (PMID 40217736, 2025). "It has been reported that the dysregulation of insulin action may be associated with the pathophysiology of schizophrenia above and beyond the side effects of pharmacological treatments." (PMID 38673334, 2024). "Central insulin action is relevant to cognition and cognitive dysfunction in schizophrenia could be linked to central insulin defects." (PMID 34108878, 2021). "The IGF2BP2 polymorphisms are associated with vulnerability to schizophrenia in a Han Chinese population and with impaired pancreatic β-cell function, including lower fasting insulin levels, which reduced glucose-stimulated insulin secretion." (PMID 33315097, 2021). "Notably, we did not replicate a previous study which demonstrated a risk increasing effect of fasting insulin on schizophrenia, however, we utilised a larger schizophrenia GWAS and different IVs." (PMID 32920595, 2021).
schizophrenia (continued). "Whilst the aim of this study was not to find association with cases for this cohort, two PES were nominally associated with schizophrenia in the ASRB - Regulation of Insulin Secretion (z = 2.262, P = 0.0237) and the Acetylcholine Binding and Downstream Events pathways (z = 2.167, P = 0.0303)." (PMID 31964963, 2020). "For example, a low level of vitamin D during childhood may be associated with schizophrenia and vitamin D may affect insulin response to glucose stimulation." (PMID 25878665, 2015). "We reasoned that due to their independent association with schizophrenia, insulin as well as specific other metabolite clusters reflect the disease process itself, and may thus help discriminate schizophrenia from other psychoses." (PMID 21429189, 2011). "Therefore, abnormal glucose–insulin signaling during a critical period of neurodevelopment, for example, in childhood and adolescence, may disrupt biological mechanisms that alter schizophrenia risk, in either a risk-decreasing or -increasing manner." (PMID 39263363, 2024). "A longitudinal study demonstrated that persistently high fasting insulin levels from 9 years of age was associated with a higher risk of developing psychosis at 24 years, indicating possible early-life origins of the observed schizophrenia-diabetes association." (PMID 37091807, 2023). "Moreover, there is evidence that schizophrenia genetic risk among insulin and glycaemic related pathways could be a target of therapeutic intervention." (PMID 36151087, 2022). "If insulin sensitivity or blood glucose were to play a causal role in social cognitive impairment, these could be novel modifiable targets for improving outcomes in schizophrenia." (PMID 35668078, 2022). "In mice, its deletion results in lower adipose tissue mass, enhanced insulin sensitivity, and neurobehavioral changes resembling schizophrenia, highlighting its role in glutamatergic signalling and circadian regulation." (PMID 41009771, 2025). "Several studies have reported significant alterations in glucose metabolism and insulin resistance among individuals with first-episode, antipsychotic-naïve schizophrenia." (PMID 40635756, 2025). "Prior investigations indicate that individuals with schizophrenia exhibit more severe blood sugar levels and insulin status than their healthy counterparts." (PMID 39324122, 2024). "Schizophrenia is characterized by substantial alterations in brain function, and previous studies suggest insulin signaling pathways, particularly involving AKT, are implicated in the pathophysiology of the disorder." (PMID 38559131, 2024). "These pathways contribute to disruptions in insulin biosynthesis, thereby increasing susceptibility to T2DM in individuals with schizophrenia compared to the general population." (PMID 39324122, 2024). "SORBS1, a major player in the insulin signaling pathway, displayed increased expression in schizophrenia patients with high inflammation." (PMID 38516266, 2024). "In particular, the gene expression changes associated with schizophrenia risk in placenta indicated EIF2 signaling pathways, inhibition of mTOR signaling, activation of the Estrogen Receptor, and Insulin secretion and receptor signaling." (PMID 37188697, 2023). "In summary, our study opens up several avenues for future research to provide a more comprehensive understanding of schizophrenia, particularly in terms of cognitive function, body measurements, medication effects, insulin levels, and lifestyle factors." (PMID 38139760, 2023). "During the treatment of schizophrenia, leptin levels and insulin levels were also positively correlated." (PMID 36090349, 2022). "For all participants with schizophrenia, ASEX score (B = 0.053, p < 0.001), age (B = −0.006, p = 0.004), female sex (B = 0.119, p = 0.015), and insulin level (B = 0.014, p = 0.044) were associated with hyperprolactinemia." (PMID 34421613, 2021).
schizophrenia (continued). "Recently, a study demonstrated the insulin signaling abnormalities in neuronal cells in first-episode drug-naïve patients with schizophrenia." (PMID 34108878, 2021). "We measured in 46 patients with schizophrenia and MetS serum levels of adiponectin insulin, leptin, TNF-α and IL-6 and compared these levels to those of patients with schizophrenia without MetS." (PMID 33066473, 2020). "Regarding both first pregnancies and all pregnancies, women with schizophrenia exhibited significantly more often than controls pathologic glucose tolerance test, initiation of insulin treatment and anemia." (PMID 30762149, 2020). "The metabolic syndrome developed during pharmacotherapy in patients with FEP or schizophrenia is a key reason for the insulin resistance of brain tissues, which is an important factor of cardiometabolic risk." (PMID 32121669, 2020). "Abnormalities in insulin signaling pathway and its components for example, PIP2/PKC/PLC activity are strongly associated with the hyperdopaminergic theory of schizophrenia." (PMID 31754139, 2019). "Neuroendocrine biomarkers, such as cortisol, insulin, leptin, pro-opiomelanocortin, prolactin and growth hormone were similarly altered in the brain and in the blood in patients with schizophrenia." (PMID 28358316, 2017). "Some authors report abnormal glucose metabolism and insulin signaling in the brain of those with schizophrenia." (PMID 25878665, 2015). "Previous studies have suggested that 30–50% of first onset schizophrenia patients show signs of impaired insulin signalling." (PMID 24244349, 2013). "We also measured the prolactin/growth hormone and insulin/growth hormone ratios as these are known to be affected in insulin resistant states, which can occur in some schizophrenia patients." (PMID 24244349, 2013). "We have also demonstrated that the levels of hormones such as insulin, cortisol, progestone, prolactin, growth hormone and chromogranin A are altered in the circulation of first onset schizophrenia patients compared to controls." (PMID 23118852, 2012). "In agreement with this, schizophrenia patients in the present study were insulin resistant and had elevated fasting serum insulin levels." (PMID 21429189, 2011). "These considerations are offering promising new approaches in the therapy of schizophrenia-related metabolic and psychopathological alterations, for example the usage of glitazones, a group of insulin sensitizing drugs." (PMID 20631894, 2010). "Insulin has been shown to increase the expression of genes that are decreased in the hippocampus in subjects with schizophrenia in neuroblastoma cells." (PMID 19772658, 2009). "Subjects with schizophrenia also had higher fasting plasma levels of glucose, insulin and cortisol and were more insulin resistant than control subjects." (PMID 19772658, 2009). "Repeated episodes of insulin-induced hypoglycemic coma for periods ranging from 45 minutes to three hours for treating opiate addiction and schizophrenia (in the 1940s) were found to have minimal long-term effects and a mortality of less than 1%." (PMID 17147466, 2006). "Considering the obtained data, one can assume the role of genetically determined disorders of mitochondrial function, energy metabolism, and insulin signaling as well as immune changes related to impaired immunoregulatory functions of IGF-1 in the pathogenesis of some instances of schizophrenia." (PMID 40416497, 2025). "The expression of IDE has been found to be significantly reduced in the dorsolateral prefrontal cortex of patients with schizophrenia compared with controls, suggesting a possible role in the disturbed insulin signaling cascades and altered neuropeptide metabolism in the disease." (PMID 37515308, 2023).